OR51B6 (olfactory receptor family 51 subfamily B member 6)
Description:
Odorant receptor.
Synonyms: HOR5'Beta6
Tractability: Antibody: UniProt places it where antibodies can reach, with medium confidence; UniProt predicts a signal peptide or a membrane-spanning region; its Gene Ontology location is reachable by antibodies, with medium confidence.
Gene: Protein-coding gene on chromosome 11 (5,351,508 to 5,352,446, forward strand). Ensembl gene ENSG00000176239.
Subcellular location: Cell membrane
Pathways (Reactome):
Sensory Perception: Expression and translocation of olfactory receptors
Gene Ontology:
Molecular function: olfactory receptor activity; signaling receptor activity
Biological process: sensory perception of smell; cellular response to lipid; detection of chemical stimulus involved in sensory perception of smell; G protein-coupled receptor signaling pathway; system process
Cellular component: membrane; plasma membrane
Genetic constraint (gnomAD): Loss-of-function variants: 0 observed, 0.21 expected, observed/expected ratio (o/e) 0, 90% interval 0 to 1.88. That is too few expected variants to judge how well the gene tolerates losing a copy. Missense variants: 487 observed, 389.68 expected, observed/expected ratio (o/e) 1.25, 90% interval 1.16 to 1.35. Synonymous variants: 149 observed, 134.15 expected, observed/expected ratio (o/e) 1.11, 90% interval 0.97 to 1.27.
Homologues: Orthologues: chimpanzee OR51B6 (96% identical), rabbit OR51B6 (89% identical), dog OR51B6 (88% identical), mouse Or51b6 (86% identical), rat Or51b6 (86% identical), mouse Or51b6b (82% identical), rat Or51b6b (80% identical). Paralogues in human: OR51B5 (70% identical), OR51B2 (68% identical), OR51B4 (67% identical), OR51G1 (51% identical), OR51G2 (51% identical), OR51V1 (48% identical), OR51L1 (47% identical), OR51A4 (46% identical), OR51A2 (45% identical), OR51A7 (45% identical), OR52K2 (45% identical), OR51M1 (45% identical), and 39 more.
Diseases named in the same sentence as OR51B6 in open-access papers:
OR51B6 is named in the same sentence as 1 disease in open-access papers, as found by Europe PMC text mining. Sharing a sentence is not in itself a finding about the gene and the disease. The quoted sentences say what the papers report.
sickle cell anemia (1 paper, 2024). "In contrast, the strongest signals in AFR, AMR, and EUR were seen in OR51B6, which corresponds to rs5006884 with known association to fetal hemoglobin (HbF) levels in sickle cell anemia, a classical example of balancing selection driven disease." (PMID 38302106, 2024).